CRP (C-reactive protein)
Diseases named in the same sentence as CRP in open-access papers (continued):
Sharing a sentence is not in itself a finding about the gene and the disease.
anemia (continued). "Anemia, elevated erythrocyte sedimentation rate (ESR), C-reactive protein (CRP), serum lactate dehydrogenase (LDH), aminotransferases, and leukopenia are common findings in others." (PMID 37884991, 2023). "Patients with higher inflammatory markers (according to CRP, NLR or their combination) had more anemia, more fever and number of infections and lower albumin as expected." (PMID 37016028, 2023). "And added that GSE reduced inflammation by lowering C-reactive protein (CRP) and cholesterol levels as well as combating anaemia and thrombocytopenia." (PMID 37985554, 2023). "Intestinal parasites, malaria, high CRP, high AGP and anemia were diagnosed in 47.6%, 4.4%, 1.9%, 28.6%, and 14.9% of participants respectively." (PMID 37974246, 2023). "A previous study found that the severity of depression was positively correlated with C-reactive protein and ferritin levels and negatively correlated with serum albumin levels, suggesting that ESRD patients with depression also have anemia and inflammation." (PMID 36825130, 2023). "Significantly, both clinical groups showed anemia, an increase in NLR, GAR, CRP, and CAR, and a decrease in AGR compared to the normal group." (PMID 37009523, 2023). "His blood investigations showed anemia (Hb 9.2g/dL), leukocytosis (WBC 25.1), and raised inflammatory markers (ESR 362mm/hour, CRP 252.3mg/L)." (PMID 37905257, 2023). "While the discriminatory ability of CRP appeared unaffected by HIV status (and ART status among PLHIV), smoking, history of previous TB, age, and BMI, AUROCs were lower among people with anemia and men." (PMID 36375640, 2023). "We report the case of a 1-month-old female infant who presented persistent high C-reactive protein (CRP) levels from birth and anemia." (PMID 38075699, 2023). "In the NNMSS, age, ethnicity, recent fever, MNP intake, inflammation (ln CRP), RBP, and glucose-6-phospate dehydrogenase were all significant predictors of anemia in children aged 6–59 mo." (PMID 37180849, 2023). "The colchicine-non-responders in our study suffered from the severe type of the disease, high ESR, anemia, SAA, CRP, renal stones, lower pyrin concentration, and higher methylation level of the MEFV gene exon 2 than colchicine-responders." (PMID 36661534, 2023). "Laboratory findings indicated that anemia and renal and liver functional tests and inflammatory markers [erythrocyte sedimentation rate (ESR) and C-reactive protein (CRP)] were normal." (PMID 37076913, 2023). "In the presented study, both in CD and UC, a negative correlation was observed between the concentration of CRP and HGB, which confirms the influence of the intensity of inflammation on the incidence of anaemia in IBD." (PMID 37048531, 2023). "The most common laboratory findings were: increased erythrocyte sedimentation rate (ESR) (31 – 100%), high C-reactive protein (CRP) (24 – 77.4%), anemia (16 – 51.6%), elevation of liver enzymes (14 – 45%) and hyperferritinemia (13 – 41.9%)." (PMID 37848930, 2023). "Among the laboratory abnormalities, the most common is the occurrence of lymphopenia with an increased number of neutrophils, thrombocytopenia, anemia, and elevated values of LDH, AST, ALT, CK, D-dimer, CRP, and decreased albumin values." (PMID 37510752, 2023). "Apart from HAZ score, age, sex, and anemia, we also assessed two putative EED inflammatory biomarkers (fecal AAT and calprotectin) and the systemic inflammatory marker (serum-CRP), along with asymptomatic parasites and protozoan carriage." (PMID 35720335, 2022). "Laboratorial features: ESR - 21.0 (12.5; 27.8) mm/h, CRP - 3.9 (0.4; 14.5) mg/l, number of patients with increased ESR - 55%, with increased - CRP 55%, with anemia - 36.4%." (PMID 36096831, 2022).
anemia (continued). "Thus, anaemia is often a reflection of a tumour-driven, cytokine-mediated, systemic inflammatory response, therefore explaining the observed inverse correlation between severity of anaemia and C-reactive protein and the modified Glasgow Prognostic Score (mGPS) for inflammation." (PMID 36032656, 2022). "Correspondingly, urea and creatinine, white blood cell (WBC), C-reactive protein (CRP), and procalcitonin values were found to be significantly higher in the patient group with anemia (p < 0.001)." (PMID 35892443, 2022). "The main factors correlated to lower physical activity and capacity in HIV-infected were low BMI, anaemia, low CD4 counts as a marker of disease progression, and increased CRP as a marker of inflammation." (PMID 35061774, 2022). "Microcytic anemia and elevation of inflammatory markers are common laboratory findings, as seen in our patients in which all but one had microcytic anemia and all had elevated inflammatory markers, especially ESR with slightly altered CRP." (PMID 36186634, 2022). "On the day of admission, there were elevated inflammatory markers (CRP 172 mg/l, erythrocyte sedimentation rate, ESR 137 mm per hour), normocytic anemia and coagulopathy." (PMID 36096831, 2022). "Microcytic anemia and ESR elevation with only slight alteration of CRP are common laboratory findings." (PMID 36186634, 2022). "Our data unveiled that TCM effectively augmented the levels of RBC and Hb and reduced the levels of ESR, hs-CRP, RF, α1-AGP, anti-CCP, IgA, IgG, and UA in RA patients with anemia." (PMID 35966735, 2022). "Laboratories disclosed anemia, thrombocytopenia, elevated erythrocyte sedimentation rate (ESR) and C-reactive protein (CRP), albumin-globulin (A-G) reversal, and sterile blood cultures." (PMID 36654579, 2022). "Laboratory data showed elevated serum immunoglobulin G4 (IgG4) levels, hypergammaglobulinemia, high C-reactive protein (CRP) levels, marked anemia, and positivity for several autoantibodies." (PMID 36140662, 2022). "In the univariate analysis, an older age, HTN, location of the abscess, anemia, albumin levels, AST levels, ALT levels, CRP levels, K. pneumoniae infection and unidentified infection were significant factors contributing to the development of low PWR levels." (PMID 36292245, 2022). "Laboratory test results showed WBC of 3.7, normocytic anaemia, high ESR of 45, and normal CRP, C3, and C4." (PMID 36199642, 2022). "Anaemia, renal impairment and elevated LDH were more frequent in patients with any AD, while elevated CRP and LDH were more frequent in patients with severe rheumatologic AD." (PMID 35377457, 2022). "Blood tests showed hyperinflammatory syndrome (ferritin 4,350 μg/L and C-reactive protein 55 mg/L) with a moderate increase in AST and ALT (2 and 1.5 times the ULN values, respectively) and mild thrombocytopenia and anemia." (PMID 36225555, 2022). "Laboratory test (the first admission) found mild normocytic anemia (Hb 10.4 g/dL), normal INR, platelet count, and CRP level." (PMID 35450101, 2022). "In the univariate analysis, a low PWR, abscess size, anemia, albumin, ALP and CRP levels, K. pneumoniae infection and unidentified infection were associated with prolonged hospitalization for more than 14 days." (PMID 36292245, 2022). "Other factors, including age, HTN, DM, the location and size of abscess, anemia, levels of albumin, AST, ALT, PT-INR, Cr, and CRP and infections with K. pneumoniae, E. coli and other organisms were not correlated with the development of pleural effusion." (PMID 36292245, 2022). "Other studies showed that patients presented with anemia, lymphopenia, thrombocytopenia, slightly abnormal creatinine and BUN levels, low albumin levels, high d-dimer, CRP, and procalcitonin levels." (PMID 34945730, 2021).
anemia (continued). "IL-6 acts on hepatocytes and induces increased production of several acute-phase proteins, including C-reactive protein (CRP), serum amyloid A (SAA), fibrinogen, and hepcidin, which account for amyloidosis, hypercoagulation, and anemia of inflammation." (PMID 34208103, 2021). "Our study observed that being overweight, obese, and having central obesity were correlated with increased odds of anemia, as well as decreased Hb, Hct, and RBC levels but increased WBC and CRP levels." (PMID 33810272, 2021). "These include normochromic and normocytic anemia, mild leukocytosis, increased erythrocyte sedimentation rate (ESR), increased C-reactive protein (CRP), and elevations in alkaline phosphatase and IgA." (PMID 34394873, 2021). "Our study observed a positive correlation between the anemia–inflammation-related dietary pattern and inflammatory biomarkers, such as WBC and CRP." (PMID 33810272, 2021). "There is some evidence implicating elevated serum CRP, elevated serum LDH and anemia as markers for clinical outcomes in solid tumors." (PMID 34417915, 2021). "Laboratory evaluation showed elevation of the erythrocyte sedimentation rate (ESR) 140 mm/first hour and C-reactive protein (CRP) 7.75 mg/dL, normocytic and normochromic anemia (Hb 10.1 g/dL), and increased serum creatinine (3.96 mg/dL) and urea (103 mg/dL)." (PMID 34123446, 2021). "Persistent splenomegaly and severe and refractory anemia, thrombocytopenia and neutropenia, as well as high levels of acute reactant markers (ESR, CRP and SAA) were consistent findings upon flares." (PMID 34399798, 2021). "Anaemia was predicted by ID, VAD, and ZnD in Chamwino and by elevated infection markers, C-reactive protein (CRP) and α-1 glycoprotein (AGP), in Kilosa." (PMID 34066852, 2021). "Laboratory evidence of inflammation includes anemia, thrombocytosis, and elevations in the inflammatory markers erythrocyte sedimentation rate (ESR) and/or C-reactive protein (CRP)." (PMID 33717128, 2021). "Positive correlations were found with anemia and active disease (PGA), CRP (>5 mg/L) and ESR (>10 mm/h) at diagnosis and follow-up." (PMID 33467587, 2021). "High C-reactive protein (CRP) levels and hematological disorders (anemia, neutropenia, and thrombocytopenia) were commonly observed." (PMID 32435626, 2020). "Interestingly, a recent report from the Biomarkers Reflecting Inflammation and Nutritional Determinants of Anemia (BRINDA) group highlighted the association between a marker of chronic (α-2 glyco-protein: AGP) but not acute (C-reactive protein: CRP) inflammation and poor linear growth in children." (PMID 32023835, 2020). "Due to genital bleeding from the primary tumor, blood data revealed severe anemia and increased erythropoietic activity (Hb = 6.7 g/dL, RDW = 21.2%, WBC = 8.8 × 103/μL, and CRP = 0.08 mg/dL)." (PMID 32807812, 2020). "Correlation coefficients above 0.7 were observed for markers of inflammation (CRP and SAA; ρ = 0.81), bone formation (P1NP and OC; ρ = 0.82) and anaemia of chronic disease (ferritin and hepcidin; ρ = 0.74), as expected." (PMID 32264972, 2020). "Laboratory findings like anemia, elevated ALP and LDH, reduced albumin, elevated ESR, CRP along with increased serum ferritin also suggest the possibility of AOSD." (PMID 32335625, 2020). "Finally, those patients who were categorised as having anaemia of another cause or without evidence of iron deficiency (ferritin < 30 μg/L and CRP ≤ 5 mg/L, n = 18) had a similar median pre-infusion haemoglobin to those with anaemia of inflammation (110 mg/L, range 103 to 115)." (PMID 32537137, 2020). "Additional significant indicators were age, CRP level, estimated glomerular filtration rate <90 mL/min/1.73 m2, WBC count, anemia, and ALT level." (PMID 33521032, 2020). "According to the results of the multivariate logistics regression analysis, we used WBC, anemia, PCT, CRP, albumin, and ALT to develop the nomogram model." (PMID 32792679, 2020).
anemia (continued). "In theory, sTfR measurement may be the most important biomarker to explain the etiology of anaemia in MM compared to more established biomarkers, such as serum ferritin, transferrin saturation, ferritin index (sTfR/log transferrin saturation), hypochromic reticulocytes and C-reactive protein (CRP)." (PMID 31683939, 2019). "Laboratory tests showed a severe anaemia (Hb 7 g/dL), lymphopenia (WBC 2960 cells/mL), and a slight c-reactive protein (CRP) alteration of 15.48 mg/L." (PMID 31351487, 2019). "Using a multivariate logistic regression, we found that individuals with increased levels of CRP and ESR had increased odds for persisting anemia at day 60 of ATT." (PMID 30718725, 2019). "The inclusion of healthy participants in a control group on the basis of acute phase protein concentrations (CRP, FRT) and serum iron concentration is unreliable to exclude subclinical characteristics of anemia." (PMID 30984307, 2019). "Laboratory examination revealed mild anemia (hemoglobin (Hb) 11.5 g/dl) and elevated levels of erythrocyte sedimentation rate (ESR) (74 mm/hour) and C-reactive protein (CRP) (13.79 mg/dl)." (PMID 31860960, 2019). "At presentation, laboratory tests revealed anemia in 8 (47%), thrombocytosis in 6 (35%), elevated erythrocyte sedimentation rate (ESR) in 9 (53%), and high C reactive protein (CRP) in 6 (35%) children." (PMID 30519287, 2018). "Participants with high ferritin group tended to be older, have lower BMI, higher C-reactive protein (CRP) and slightly more anemia." (PMID 29649107, 2018). "The main findings from standard blood tests were CRP elevation (n = 11, 84.6%), ESR elevation (n = 9, 69.2%), serum fibrinogen elevation (n = 7, 70.0%), and anaemia (n = 5, 38.5%)." (PMID 30020975, 2018). "RDW positively correlates with inflammatory markers such as C-reactive protein (CRP) and erythrocyte sedimentation rate (ESR) even after excluding anemia." (PMID 30363719, 2018). "The most common laboratory findings in AITL include elevated LDH (60%), elevated C-reactive protein (CRP; 35%), anemia (33%), and hypergammaglobulinemia (30%)." (PMID 29673407, 2018). "The present study demonstrated an association between high serum levels of AAT and more severe anemia, increased WBC and neutrophil counts, as well as altered CRP levels." (PMID 29163550, 2017). "The most frequent abnormal blood tests among cancer patients were high inflammatory markers (CRP or erythrocyte sedimentation rate (ESR)), high monocyte count, anaemia, low lymphocyte count, hypo-albuminaemia and high alkaline phosphatase." (PMID 29202799, 2017). "High levels of WBC, N%, CRP, ESR and anemia probably reflected the severity of ongoing inflammation in patients with KD." (PMID 28320400, 2017). "Laboratory data showed anemia, normal platelet and leucocyte counts with elevated lactate dehydrogenase (LDH), aspartate aminotransferase (AST) and C-reactive protein (CRP)." (PMID 29187222, 2017). "Anemia and thrombocytopenia resolved, and markers of inflammation such as ESR and CRP normalized within the first few weeks." (PMID 28183278, 2017). "Elevation in the serum C-reactive protein (CRP) level, anemia (hemoglobin < 12 g/dL) and thrombocytopenia (platelet < 140 k/μL) were observed in 70.6%, 39.7% and 12.9% of patients, respectively, in the NTM-PI group." (PMID 29176633, 2017). "In total, 23 national and 2 urban national representative publications reporting on anemia, IDA, and elevated CRP or AGP in PSC or WRA met our inclusion criteria." (PMID 27827838, 2016). "Anemia, increases in serum alkaline phosphatase, AST (>400 IU/L), ALT (> 200 IU/L) and CRP (mg/dL), and prolongation of prothrombin time (PT) (INR ≥1.3) and aPTT (>60 sec) were associated with death." (PMID 28033338, 2016). "Previous studies have shown that higher C-reactive protein (CRP), erythrocyte sedimentation rate (ESR), thrombocytosis and anemia are predictive for a TAB result compatible with GCA." (PMID 27558589, 2016).
anemia (continued). "Her tests revealed anemia (HCT = 23%, HGB = 7.2 mg/dL), a low WBC count, an elevated ESR (>100 mm/h), and CRP = 71.4 mg/L (0.0–5.0 mg/L); thus, she received 1 RBC unit for treating anemia." (PMID 27504121, 2016). "Patients with TINU have been reported to have anemia, eosinophilia, elevations in ESR and CRP, sterile pyuria and abnormal elevations in serum, and urine beta-2 microglobulin." (PMID 26446047, 2015). "Laboratory findings consistent with KD were leucocytosis with neutrophilia, anaemia, late thrombocytosis, elevated ESR and CRP, hypoalbuminemia, hyponatremia, elevated serum transaminases and gamma-glutamyl transpeptidase." (PMID 25890055, 2015). "Those with more severe anemia were also more likely to have more advanced immunodeficiency, higher HIV viral loads, higher CRP levels, and lower eGFRs." (PMID 26730391, 2015). "Laboratory tests revealed a high leucocyte count level (white blood cell, WBC =21×109/L), high C-reactive protein level (CRP=189.6mg/L), slight anemia (hemoglobin, HGB =96g/L), and low serum potassium level (K=3.26mmol/L)." (PMID 26385213, 2015). "Laboratory finding on admission revealed relative neutrophil leucocytosis, hypochromic microcytic anaemia (haemoglobin 10.5 g %) with high Erythrocyte sedimentation rate (ESR) and C-reactive protein (CRP)." (PMID 25888831, 2015). "Laboratory results revealed blood count abnormalities (thrombocytopenia and normocytic anemia), hypoalbuminemia, elevation of erythrocyte sedimentation rate (ESR), C-reactive protein (CRP), ferritin and γ-globulin (polyclonal)." (PMID 25671135, 2015). "Laboratory abnormalities included the evidence of systemic inflammation with increased erythrocyte sedimentation rate (ESR) and C-reactive protein (CRP) and mild elevation of hepatic transaminase levels and hypochromic anemia in all patients." (PMID 25243162, 2014). "In multivariate analysis, anemia, baseline EBV-DNA copy level, baseline CRP, and CRP kinetic statues were independent prognostic factors." (PMID 24130817, 2013). "Laboratory abnormalities include anemia, thrombocytosis, polyclonal hypergammaglobulinemia, and elevated ESR, CRP, or IgG4." (PMID 23424593, 2013). "Blood tests should be evaluated for evidence of an acute phase response (elevated Erythrocyte Sedimentation Rate [ESR] and C-Reactive Protein [CRP]) and normochromic normocytic anaemia, and the diagnosis is confirmed on imaging." (PMID 23986869, 2013). "Analyzed factors included age, sex, metastasis at presentation, metastasis sites (i.e., bone, liver, and lung), number of involved sites, anemia, serum LDH, baseline EBVDNA, baseline CRP level, and CRP kinetics status." (PMID 24130817, 2013). "Extensive laboratory workup was significant for a microcytic hypochromic anemia, elevated erythrocyte sedimentation rate (ESR) and C-reactive protein (CRP), and an abnormal lipid panel." (PMID 23555066, 2013). "Therefore, the temporal relation between exposures and outcomes (anemia or Hb concentrations) could not be established to ensure that micronutrient deficiencies and elevations in CRP concentrations precede the outcomes." (PMID 22574149, 2012). "Hyper-IL-6 syndromes are characterized by elevated serum levels of IgG, IgA, IgM, and C-reactive protein (CRP); thrombocytosis; anemia; hypoalbuminemia; hypocholesterolemia." (PMID 22719769, 2012). "Unlike IgG4-RD, hyper-IL-6 syndromes are characterized by elevated serum levels of IgG, IgA, IgM, and C-reactive protein (CRP); thrombocytosis; anemia; hypoalbuminemia; hypocholesterolemia." (PMID 22719769, 2012). "On further evaluation, laboratory tests revealed an anemia, raised erythrocyte sedimentation rate (ESR), C-reactive protein (CRP), blood urea nitrogen (BUN) and creatinine." (PMID 20076780, 2009). "Standard laboratory studies demonstrated mild anemia (Ht = 32.2% and Hb = 9.7 mg/dl) and slightly increased erythrocyte sedimentation rate (ESR = 47 mm/h) and C-reactive protein (CRP = 2.8 mg/l)." (PMID 19203367, 2009).